C16orf89 (chromosome 16 open reading frame 89)
Synonyms: MGC45438
Tractability: Antibody: UniProt places it where antibodies can reach, with high confidence; UniProt predicts a signal peptide or a membrane-spanning region; its Gene Ontology location is reachable by antibodies, with medium confidence.
Gene: Protein-coding gene on chromosome 16 (5,044,122 to 5,066,110, reverse strand). Ensembl gene ENSG00000153446.
Subcellular location: Secreted
Gene Ontology:
Molecular function: protein homodimerization activity
Cellular component: cytosol; extracellular exosome; membrane; extracellular region
Genetic constraint (gnomAD): Loss-of-function variants: 53 observed, 39.61 expected, observed/expected ratio (o/e) 1.34, 90% interval 1.07 to 1.68. The upper end of that interval is the gene's LOEUF score, 1.68, which puts it in group 6 of 6, group 1 being the genes least tolerant of losing a copy. Missense variants: 534 observed, 427.39 expected, observed/expected ratio (o/e) 1.25, 90% interval 1.16 to 1.34. Synonymous variants: 212 observed, 186.14 expected, observed/expected ratio (o/e) 1.14, 90% interval 1.02 to 1.28.
Homologues: Orthologues: macaque C20H16orf89 (95% identical), chimpanzee C16H16orf89 (89% identical), dog C16orf89 (76% identical), pig C16orf89 (75% identical), rat C10h16orf89 (69% identical), mouse AU021092 (68% identical), rabbit C16orf89 (68% identical), guinea pig C16orf89 (61% identical), zebrafish C3H16orf89 (36% identical).
Diseases named in the same sentence as C16orf89 in open-access papers:
C16orf89 is named in the same sentence as 4 diseases in open-access papers, as found by Europe PMC text mining. Sharing a sentence is not in itself a finding about the gene and the disease. The quoted sentences say what the papers report.
esophageal cancer (1 paper, 2021). A primary or metastatic malignant neoplasm involving the esophagus. "Our analysis showed that following five genes were most significantly downregulated in esophageal cancer: C16orf89 (9.78E−08), AR (1.01E−07), CKB (1.17E−07), ADH1B (1.79E−07), and NCAM1 (2.15E−07)." (PMID 33828156, 2021). "With respect to downregulated genes, C16orf89, AR, CKB, ADH1B, and NCAM1 were the leading downregulated genes in patients with esophageal cancer." (PMID 33828156, 2021).
thyroid (1 paper, 2021). "The 11 selected thyroid-specific RNA transcripts (TPO, TG, GFRA2, IYD, PDE8B, WDR86, C16orf89, DGKI, DIO2, TSHR, and PAX8) were amplified from healthy volunteers and thyroid patients." (PMID 34512731, 2021).
neoplasm (2 papers, 2021 to 2024). A benign or malignant tissue growth resulting from uncontrolled cell proliferation. "CKS1B+ neoplasm, C16orf89+ neoplasm, CST6+ neoplasm, H2AC6+ neoplasm and MTND2P13+ neoplasm all demonstrate heightened tumour stemness." (PMID 38946232, 2024).
C16orf89 also shares sentences with these, for which no sentence is quoted: adenocarcinoma (1 paper).